SPEG (striated muscle enriched protein kinase)
Description:
Isoform 3 may have a role in regulating the growth and differentiation of arterial smooth muscle cells.
Synonyms: APEG-1; APEG1; KIAA1297; MGC12676; SPEGalpha; SPEGbeta; BPEG; MYLK6; CNM5
Tractability: Small molecule: it belongs to a druggable protein family.
Gene: Protein-coding gene on chromosome 2 (219,434,843 to 219,493,629, forward strand). Ensembl gene ENSG00000072195.
Subcellular location: Nucleus (Isoform 3)
Subcellular location (Human Protein Atlas): Vesicles
Gene Ontology:
Molecular function: protein binding; protein kinase activity; ATP binding; protein serine kinase activity; protein serine/threonine kinase activity
Biological process: muscle cell differentiation; muscle organ development; negative regulation of cell population proliferation
Cellular component: nucleus
Genetic constraint (gnomAD): Loss-of-function variants: 113 observed, 257.05 expected, observed/expected ratio (o/e) 0.44, 90% interval 0.38 to 0.51. The upper end of that interval is the gene's LOEUF score, 0.51, which puts it in group 2 of 6, group 1 being the genes least tolerant of losing a copy. Missense variants: 4,194 observed, 4,226 expected, observed/expected ratio (o/e) 0.99, 90% interval 0.97 to 1.02. Synonymous variants: 1,958 observed, 1,825.5 expected, observed/expected ratio (o/e) 1.07, 90% interval 1.03 to 1.11.
Gene-disease validity (ClinGen):
ClinGen rates the evidence that SPEG causes each of these diseases.
myopathy, centronuclear, 5 (autosomal recessive): Definitive. Any autosomal recessive centronuclear myopathy in which the cause of the disease is a mutation in the SPEG gene.
Homologues: Orthologues: chimpanzee SPEG (99% identical), macaque SPEG (93% identical), dog SPEG (92% identical), mouse Speg (91% identical), rat Speg (91% identical), Caenorhabditis elegans unc-22 (14% identical), Drosophila melanogaster bt (8% identical), Drosophila melanogaster zormin (4% identical), Caenorhabditis elegans dim-1 (2% identical). Paralogues in human: OBSCN (13% identical), HMCN1 (12% identical), MYPN (10% identical), PALLD (8% identical), IGFN1 (6% identical), ALPK3 (6% identical), CCDC141 (4% identical), MYOT (3% identical), SPEGNB (2% identical).
Diseases named in the same sentence as SPEG in open-access papers:
SPEG is named in the same sentence as 48 diseases in open-access papers, as found by Europe PMC text mining. Sharing a sentence is not in itself a finding about the gene and the disease. The quoted sentences say what the papers report.
centronuclear myopathy (14 papers, 2020 to 2024). Centronuclear myopathy (CNM) is an inherited neuromuscular disorder characterized by clinical features of a congenital myopathy and centrally placed nuclei on muscle biopsy. "CCDC78 mutations and SPEG mutations are implicated in centronuclear myopathy 4 and centronuclear myopathy 5, respectively." (PMID 38988494, 2024). "Striated muscle preferentially expressed protein kinase (SPEG) variants have been reported to cause centronuclear myopathy associated with cardiac diseases." (PMID 37673875, 2023). "SPEG mutations have been found in patients with centronuclear myopathy which is an inherited neuromuscular disorder characterized by clinical features of a congenital myopathy and centrally placed nuclei on muscle biopsy." (PMID 36685827, 2022). "Striated preferentially expressed protein kinase (SPEG), a myosin light chain kinase, is mutated in centronuclear myopathy (CNM) and/or dilated cardiomyopathy." (PMID 35763354, 2022). "Mutations in striated preferentially expressed protein kinase (SPEG), a member of the myosin light chain kinase protein family, are associated with centronuclear myopathy (CNM), cardiomyopathy, or a combination of both." (PMID 34072258, 2021). "Mutations in SPEG have recently been identified in patients with centronuclear myopathies (CNMs), a group of disorders characterized by severe muscle weakness with respiratory impairment, ophthalmoplegia, and scoliosis." (PMID 32925938, 2020). "Moreover, SPEG is linked to centronuclear myopathy, while PRKCZ is associated with adenocarcinoma of the large intestine." (PMID 39434882, 2024). "Finally, MTM1 was found to interact with the striated muscle enriched protein kinase SPEG; mutations in SPEG have been linked to centronuclear myopathies with disruptions of triadic structures and impairment of ECC." (PMID 35454077, 2022). "Striated muscle preferentially expressed protein kinase (SPEG) is required for myocyte cytoskeletal development, and mutations in SPEG gene are related with centronuclear myopathy." (PMID 34959561, 2021). "Autosomal‐recessive mutations in SPEG (striated muscle preferentially expressed protein kinase) have been linked to centronuclear myopathy with or without dilated cardiomyopathy (CNM5)." (PMID 38725372, 2024).
dilated cardiomyopathy (12 papers, 2018 to 2025). Cardiomyopathy which is characterized by dilation and contractile dysfunction of the left and right ventricles. "The SPEG gene encodes a myosin light chain kinase and regulator of cardiac calcium homeostasis with mutations causing dilated cardiomyopathy, atrial fibrillation, and heart failure." (PMID 39774334, 2025). "In conclusion, novel compound heterozygous SPEG variants were identified in an infant developing dilated cardiomyopathy who had transient hypotonia." (PMID 37673875, 2023). "Here, we report novel SPEG compound heterozygous pathological variants in a neonate with severe dilated cardiomyopathy and relatively mild hypotonia." (PMID 37673875, 2023). "We have previously demonstrated that constitutive SPEG-deficient mice develop dilated cardiomyopathy (DCM), and a majority of them die in utero or shortly after birth due to heart failure." (PMID 35763354, 2022). "Patients with SPEG mutations have skeletal muscle weakness as well as dilated cardiomyopathy (DCM)." (PMID 35293586, 2022). "Patients with SPEG mutations manifest both skeletal muscle and cardiac (e.g. dilated cardiomyopathy) abnormalities, and heart dysfunction could explain the early lethality seen in our spega/b zebrafish." (PMID 35293586, 2022). "Furthermore, human loss-of-function mutations in SPEG are associated with dilated cardiomyopathy [as reviewed in] suggesting reduced SPEG activity is a risk factor for cardiac pathology." (PMID 35069264, 2021). "We have previously linked recessive variants in SPEG with CNM, CM or dilated cardiomyopathy (DCM), CNM and DCM often presenting together." (PMID 38725372, 2024). "Striated muscle-enriched protein kinase (SPEG) E1680K homozygous mutant hiPSC-CMs recapitulate the hallmarks of dilated cardiomyopathy (DCM), confirming that SPEG E1680K is a novel DCM-causing mutation." (PMID 36895064, 2023). "In the same study, the authors demonstrated the implication of SPEG locus in dilated cardiomyopathy." (PMID 35563595, 2022). "In addition, XLMTM patients carrying SPEG mutation have a higher probability of dilated cardiomyopathy due to the interaction between MTM1 and SPEG as well as the wide distribution of SPEG in cardiomyocytes." (PMID 38988494, 2024). "Although several cases of dilated cardiomyopathy linked to SPEG mutations were reported either associated to myopathy or not, only one case of non-compaction and neuropathy was reported." (PMID 35563595, 2022).
cardiomyopathy (11 papers, 2015 to 2024). A disease of the heart muscle or myocardium proper. "Striated Muscle Enriched Protein Kinase (SPEG) that is associated with cardiomyopathy and COVID-19 mortality." (PMID 36143338, 2022). "Mutations in both gene DES and SPEG are reported to be associated with cardiomyopathy." (PMID 33536081, 2021). "Indeed, loss of function models for SPEG and identified human mutations have been linked to a number of cardiomyopathies." (PMID 33801198, 2021). "CNM with cardiomyopathy is linked to SPEG and DNM2 mutations, but, in many cases, the genetic cause is unknown." (PMID 26935107, 2016). "Myopathies can be associated to cardiac phenotypes, and some genes are implicated in both myopathy and cardiomyopathy, such as TTN and SPEG." (PMID 39625536, 2024). "In this study, BLITZ revealed several putative cavin interactors that have also been shown to be involved in cardiomyopathies and/or skeletal myopathies, including the membrane protein Dystrophin, the triad-associated proteins Bin1, Cypher/ZASP, and SPEG." (PMID 33591275, 2021). "SPEG knockout mice develop severe cardiomyopathy and heart failure." (PMID 33801198, 2021). "SPEG may have fiber type–specific and tissue-specific roles, which may affect the efficacy of DNM2 reduction in rescuing Speg-related myopathy and cardiomyopathy phenotypes." (PMID 35763354, 2022).
heart failure (8 papers, 2015 to 2025). Inability of the heart to pump blood at an adequate rate to meet tissue metabolic requirements. "To date, over 21 patients have been identified with recessive SPEG mutations, with 11 deaths associated with respiratory or cardiac failure." (PMID 35763354, 2022). "Functional annotations show the SPEG gene to be essential for cardiac function in particular, with deficiency of this gene reported to result in heart failure." (PMID 32600451, 2020). "Altered Ca2+ cycling and cardiac contraction is well known in heart failure and was also demonstrated in iPSC-CMs with mutations causing defective sarcomere structures: S635A- in RBM20, E1680K in SPEG R173W in TNNT2." (PMID 37349842, 2023). "Loss of SPEG in mouse hearts causes JPH2 dephosphorylation, although the phosphorylation levels of RyR2 at the sites of S2808 and S2814, which were known to contribute to Ca2+ dysregulation in heart failure, were unaltered." (PMID 34072258, 2021). "Moreover, isoproterenol reduces SPEG mRNA levels in mouse hearts, possibly contributing to ensuing heart failure phenotype and pathologically altered calcium handling." (PMID 33801198, 2021). "Further, administration of wild-type (WT) CPCs into the fetal hearts of SPEG-deficient mice has been shown to promote CPC engraftment and differentiation and enhance myocardial maturation, which rescues these mice from neonatal heart failure." (PMID 34072258, 2021).
COVID-19 (5 papers, 2022 to 2025). A disease caused by infection with severe acute respiratory syndrome coronavirus 2. "Through integrative screening of genetic factors associated with both hypertension and severe COVID-19, we revealed that the cis-eQTL rs12474050 of SPEG is a potential host factor predisposing to higher DBP and severe COVID-19 in women." (PMID 36685827, 2022). "Our integrative genetic screening of SNPs associated with both hypertension and severe COVID-19 revealed that the cis-eQTL rs12474050 of SPEG was potentially associated with severe COVID-19 in women." (PMID 36685827, 2022). "Our analyses reveal that only one cis-eQTL, rs12474050, mapped to the gene striated preferentially expressed protein kinase (SPEG) encoding the protein SPEG, shown significant, sex-biased association with severe COVID-19 in women." (PMID 36685827, 2022). "Mutations in genes such as the heterozygous desmin gene (DES) and Striated Muscle Enriched Protein Kinase (SPEG), associated with cardiovascular disorders, have been recognized as possible risk factors for COVID-19 mortality." (PMID 40002898, 2025). "The results of these genetic factors in the genes (TLR7, UNC13D, DES, SPEG, LZTFL1, ABO, ILRUN, and CACFD1) provide substantial insights into the genesis of cardiovascular issues linked with COVID-19." (PMID 40002898, 2025). "Detailed evaluation of SPEG expression in each individual sample revealed that three out of six COVID-19 females shown higher upregulation of SPEG in cardiomyocytes, with another 2 COVID-19 females contained <100 cardiomyocytes." (PMID 36685827, 2022). "We thus investigated the potential link between sex-biased expression of SPEG and COVID-19 severity in females." (PMID 36685827, 2022). "Our finding suggested that SPEG plays a protective role in heart damage of female COVID-19 patients." (PMID 36685827, 2022). "When compared COVID-19 females with COVID-19 males, the SPEG expression is higher in females (fold change = 1.55), although the multiple adjusted p-value is not significant (p = 0.3)." (PMID 36685827, 2022). "Taken together, our analyses suggest the involvement of SPEG in both hypertension and severe COVID-19 in women, which provides new insights for sex-biased effect of severe COVID-19 in women." (PMID 36685827, 2022). "Coincidently, we revealed that upon SARS-CoV-2 infection the expression of SPEG was upregulated in cardiomyocytes, implicating the potential damage in heart in COVID-19." (PMID 36685827, 2022). "The potential involvement of SPEGNB in both hypertension and severe COVID-19 as well as it is relationship with SPEG warrants for further study." (PMID 36685827, 2022). "Meanwhile, among 12 COVID-19 males, there are two COVID-19 males with no cardiomyocytes detected in the single cell data, seven COVID-19 males demonstrated lower expression of SPEG, and two male COVID-19 individuals displayed higher SPEG expression comparable to COVID-19 females." (PMID 36685827, 2022). "The lack of enough cardiomyocytes in the two female COVID-19 individuals and the higher expression of SPEG in two COVID-19 males are the reason why the insignificant difference at sample level was observed between COVID-19 females and males in terms of SPEG expression." (PMID 36685827, 2022). "The SNP rs12474050 (sex-biased differential association p = 1.8e-4) is a cis-eQTL of SPEG and emerged with suggestive association with severe COVID-19 in women (p = 1.8e-4; beta = 0.36; se = 0.10) but not in men (p = 0.23; beta = –0.08; se = 0.07)." (PMID 36685827, 2022). "In addition, SPEG was upregulated in cardiomyocytes of female COVID-19 patients compared to both healthy females and males." (PMID 36685827, 2022). "This might be due to the important functions of SPEG in heart, especially for its potential protective roles in cardiomyocytes in COVID-19." (PMID 36685827, 2022).
COVID-19 (continued). "The significant difference for VSMCs may be driven by two COVID-19 males with more VSMCs showing relatively higher expression of SPEG compared to all other healthy individuals." (PMID 36685827, 2022). "Taken together, the expression of SPEG is influenced by sex and SARS-CoV-2 infection, and SPEG is a critical host factor involved in severe COVID-19 in women." (PMID 36685827, 2022). "Since rs12474050*T was only found suggestively associated with severe COVID-19 in females but not in males, we questioned whether SPEG was differentially expressed between sex in muscle skeletal, heart atrial appendage, and heart left ventricle, as well as breast mammary tissue." (PMID 36685827, 2022). "Based on the abundant pieces of information for critical role of SPEG in cardiovascular system, we confirmed the enhanced expression of SPEG in female but not male would be protective against severe COVID-19." (PMID 36685827, 2022). "In addition, COVID-19 females but not COVID-19 males demonstrated significantly higher expression of SPEG compared to these healthy females and males (all p values <1e-36)." (PMID 36685827, 2022). "The study reveals that SPEG expression is naturally higher in female heart tissue and becomes further upregulated during SARS-CoV-2 infection, particularly in cardiomyocytes, which may explain why women experience more severe cardiovascular complications from COVID-19." (PMID 40901358, 2025).
Insulin resistance (4 papers, 2020 to 2025). Increased resistance towards insulin, that is, diminished effectiveness of insulin in reducing blood glucose levels. "Insulin resistance due to PKBα/β deficiency also diminished the presence of SPEG in the PAS immunoprecipitates." (PMID 32367034, 2020). "Finally, C1orf145 was associated with blood pressure, and SPEG appears to participate in diabetic cardiomyopathy through insulin resistance." (PMID 41159936, 2025). "Myocardial insulin resistance elicited by the cardiac-specific PKB inactivation impairs phosphorylation of SPEG and SERCA2a, and results in cardiac dysfunction." (PMID 39872684, 2022). "In summary, we show that cardiac insulin resistance impairs calcium homeostasis via the PKB − SPEG − SERCA2a pathway, which contributes to the development of diabetic cardiomyopathy." (PMID 32367034, 2020). "We next investigated how insulin resistance affects the SPEG–SERCA2a signaling nexus." (PMID 32367034, 2020). "Insulin resistance in this model also significantly impaired insulin-stimulated phosphorylation of PKB, SPEG and SERCA2a." (PMID 32367034, 2020). "Taken together, these data show that SPEG is a target of the insulin−PI 3-kinase−PKB signaling pathway in the heart, and insulin resistance impaired its PAS-reactive phosphorylation in the heart." (PMID 32367034, 2020).
atrial fibrillation (3 papers, 2021 to 2025). A disorder characterized by an electrocardiographic finding of a supraventricular arrhythmia characterized by the replacement of consistent P waves by rapid oscillations or fibrillatory waves that vary in size, shape and timing and are accompanied by an irregular ventricular response. "Decreased SPEG protein levels increase the susceptibility to development of atrial fibrillation (AF), which might become a target for AF treatment." (PMID 40297177, 2025).
congenital myopathy (3 papers, 2022 to 2024). "Very recently, a zebrafish model of SPEG-related CNM has been developed using CRISPR-Cas9 genome editing following on from the discovery that bi-allelic variants in SPEG cause congenital myopathy." (PMID 39425123, 2024). "Consistent with our results, SPEG deficiency in skeletal muscle was found to cause defective calcium handling and excitation-contraction coupling, further lead to congenital myopathies." (PMID 35847024, 2022).
Cognitive impairment (2 papers, 2021 to 2022). Abnormal cognition is characterized by deficits in thinking, reasoning, or remembering. "Striated Muscle Enriched Protein Kinase (SPEG) and UBE2L3 that may be structurally and functionally related to Ubiquitin Conjugating Enzyme E2 G1 (UBE2G1) were differentially methylated genes associated with cognitive impairment and circulating UBE2G1 transcripts may have potential as biomarkers." (PMID 34182925, 2021).
diabetic cardiomyopathy (2 papers, 2020 to 2025). Diabetic cardiomyopathy is a disorder of the heart muscle in people with diabetes. "Impairment of this PKB − SPEG signaling nexus may contribute to the development of diabetic cardiomyopathy." (PMID 32367034, 2020). "SPEG may serve as a new target to modulate SERCA2a activation for treatment of diabetic cardiomyopathy." (PMID 32367034, 2020).
pharyngitis (2 papers, 2020 to 2023). Inflammation of the throat most often caused by viral and bacterial infections. "In Spain, the isolates of s.pyogenes with emm1.0 genotype, associated with pharyngitis, carried speA, speG and speJ genes, but did not carry speC, speH, speI or ssa genes." (PMID 32660436, 2020).
abscess (1 paper, 2020). An inflammatory process characterized by the accumulation of pus within a newly formed tissue cavity which is the result of a bacterial, fungal, or parasitic infection or the presence of a foreign body. "However, Thurlow’s study also shows that WT USA300, isogenic ΔACME and ΔarcΔspeG mutants have similar viable CFU per abscess in a skin infection model, suggesting that speG is dispensable without ACME-Arc." (PMID 32085445, 2020).
C. perfringens infection (1 paper, 2021). "In our study, at Day 5 post C. perfringens infection, FLNB and SPEG were significantly upregulated, suggesting the association with increased cytoskeletal network activities and myocyte repairing/development." (PMID 34959561, 2021).
centronuclear myopathy type 5 (1 paper, 2022). "Firstly, mutations in the SPEG gene have been identified in patients with centronuclear myopathy type 5 (phenotype MIM number 615959) with an autosomal recessive inheritance pattern." (PMID 35563595, 2022).